PAMR1 (peptidase domain containing associated with muscle regeneration 1)
Description:
May play a role in regeneration of skeletal muscle.
Synonyms: RAMP; FP938; DKFZP586H2123
Tractability: Small molecule: it belongs to a druggable protein family. Antibody: UniProt places it where antibodies can reach, with high confidence; UniProt predicts a signal peptide or a membrane-spanning region; its Gene Ontology location is reachable by antibodies, with medium confidence.
Gene: Protein-coding gene on chromosome 11 (35,431,823 to 35,530,300, reverse strand). Ensembl gene ENSG00000149090.
Subcellular location: Secreted
Gene Ontology:
Molecular function: calcium ion binding
Cellular component: extracellular region
Genetic constraint (gnomAD): Loss-of-function variants: 65 observed, 62.71 expected, observed/expected ratio (o/e) 1.04, 90% interval 0.85 to 1.27. The upper end of that interval is the gene's LOEUF score, 1.27, which puts it in group 5 of 6, group 1 being the genes least tolerant of losing a copy. Missense variants: 798 observed, 832.12 expected, observed/expected ratio (o/e) 0.96, 90% interval 0.9 to 1.02. Synonymous variants: 292 observed, 316.49 expected, observed/expected ratio (o/e) 0.92, 90% interval 0.84 to 1.02.
Homologues: Orthologues: chimpanzee PAMR1 (99% identical), macaque PAMR1 (98% identical), rabbit PAMR1 (93% identical), pig PAMR1 (92% identical), mouse Pamr1 (90% identical), rat Pamr1 (90% identical), dog PAMR1 (89% identical), guinea pig PAMR1 (89% identical), tropical clawed frog pamr1 (67% identical), zebrafish pamr1b (49% identical), zebrafish pamr1a (43% identical). Paralogues in human: F2 (17% identical).
Diseases named in the same sentence as PAMR1 in open-access papers:
PAMR1 is named in the same sentence as 21 diseases in open-access papers, as found by Europe PMC text mining. Sharing a sentence is not in itself a finding about the gene and the disease. The quoted sentences say what the papers report.
breast carcinoma (3 papers, 2019 to 2021). "Peptidase domain containing associated with muscle regeneration 1 (PAMR1) is frequently lost in breast cancer samples and is considered as a tumor suppressor." (PMID 34671559, 2021). "Methylation inactivation of tumor suppressor genes such as P3H2 and PAMR1 were involved in the pathogenesis of breast cancer, but loss of these genes may be important for pathogenesis of GBM." (PMID 31137733, 2019). "PAMR1 is also inactivated by promoter hypermethylation in breast cancer, so it has been considered as a tumor suppressor." (PMID 34671559, 2021). "Many studies have proven that overexpression of PAMR1 markedly suppresses cell growth, especially in breast cancer, polycystic ovary syndrome, EC, and CC." (PMID 34834529, 2021). "In human malignant tumors, the expression of PAMR1 is reduced in skin squamous cell carcinoma tissues and is frequently lost in breast cancer samples (20.8%–58.3%)." (PMID 34671559, 2021). "Previous studies had identified PAMR1 as a putative tumor suppressor in breast cancer." (PMID 34671559, 2021).
cervical cancer (2 papers, 2021 to 2023). A primary or metastatic malignant neoplasm involving the cervix. "The expression of PAMR1 was downregulated in cervical cancer tissues and was associated with the survival of patients." (PMID 34671559, 2021). "Moreover, the low expression of PAMR1 is associated with poor prognosis of patients with cervical cancer, endometrial cancer, lung cancer, or liver hepatocellular cancer." (PMID 34671559, 2021). "We also analyzed the expression of PAMR1 in 31 pairs of cervical cancer and adjacent normal epithelial tissues." (PMID 34671559, 2021). "Here, KEGG analysis revealed that MYC target and mTORC1 signaling pathways were potentially suppressed by PAMR1 in cervical cancer." (PMID 34671559, 2021). "Taken together, these findings suggested that PAMR1 inhibited the proliferation, migration, and invasion of cervical cancer cells." (PMID 34671559, 2021). "We found that PAMR1 was one of most downregulated DEGs in invasive cervical cancer (p = 3.13e-6, logFC = −3.635)." (PMID 34671559, 2021). "In order to confirm the relevance between PAMR1 and these target genes in cervical cancer tissues, we analyzed TCGA-CESC data and GEO microarray data (GSE44001)." (PMID 34671559, 2021). "The results showed that overexpression of PAMR1 significantly inhibited cervical cancer cell growth." (PMID 34671559, 2021). "DEG analysis based on the data from the GEO database and functional assays identified PAMR1 as a potential biomarker negatively correlated with cervical cancer invasion." (PMID 34671559, 2021). "CCK8, Transwell, and wound-healing assays demonstrated that knockdown of PAMR1 facilitated the proliferation, migration, and invasion of cervical cancer cells." (PMID 34671559, 2021). "In conclusion, our study revealed the suppressor role of PAMR1 in cervical cancer, providing a new insight into the molecular mechanism of cervical cancer progression." (PMID 34671559, 2021). "Basic experiments showed that PAMR1 inhibited the proliferation, invasion, and migration of cervical cancer cells." (PMID 34671559, 2021). "Our study highlights the importance of PAMR1 in regulating invasion and migration of cervical cancer cells." (PMID 34671559, 2021). "In this study, we found that the expression of PAMR1 was not only lower in cervical cancer compared with normal cervix tissues from the TCGA database and IHC staining but also decreased in other malignant tumors, such as COAD, HNSC, KICH, and LUAD." (PMID 34671559, 2021). "Public database and immunohistochemical (IHC) analysis showed that the expression level of PAMR1 in cervical cancer tissues was lower than that in normal cervix tissues and was negatively related to clinicopathologic features." (PMID 34671559, 2021). "In this study, we revealed that the expression of PAMR1 was not only decreased in cervical cancer samples, but also negatively related to the individual cancer stage and prognosis of cervical cancer patients." (PMID 34671559, 2021). "In cervical cancer cell lines, the mRNA expression of PAMR1 was lower compared with that in normal cervical epithelial cell line H8." (PMID 34671559, 2021). "The score for PAMR1 was significantly lower in cervical cancer tissues than in adjacent normal tissues, and the protein level of PARM1 was decreased in patients who had positive lymph node metastasis." (PMID 34671559, 2021). "Moreover, GO analysis showed the biological process, cellular component, and molecular function of PAMR1 in cervical cancer." (PMID 34671559, 2021). "However, PAMR1 had lower expression in metastatic cervical cancer samples than in primary cervical cancer samples by using TNM plotter." (PMID 34671559, 2021). "In our present study, we identified PAMR1 as an invasion-related regulator in cervical cancer." (PMID 34671559, 2021). "We also investigated the effect of PAMR1 on the biological behavior of cervical cancer cells." (PMID 34671559, 2021).
cervical cancer (continued). "The high expression of PAMR1 also predicted a better prognosis of cervical cancer patients." (PMID 34671559, 2021). "We assessed the expression of PAMR1 in cervical cancer patients by analyzing a public database." (PMID 34671559, 2021). "In vitro functional assays showed that silencing PAMR1 could significantly promote proliferation, migration and invasive activities in cervical cancer cells." (PMID 34671559, 2021). "In summary, we identified PAMR1 as an invasion-related regulator in cervical cancer." (PMID 34671559, 2021). "The expression of PAMR1 was lower in cervical cancer compared with normal cervix uteri samples." (PMID 34671559, 2021). "Furthermore, we also explored the possible signaling pathways for PAMR1 in cervical cancer." (PMID 34671559, 2021). "Normal cervical epithelial samples exhibited stronger staining of PAMR1 than both CIN and cervical cancer tissues." (PMID 34671559, 2021). "Besides, PAMR1 could inhibit the proliferation, migration, and invasion of cervical cancer cells." (PMID 34671559, 2021). "Next, we detected the protein level of PAMR1 via IHC in a group of 138 samples which included 40 normal cervical epithelial, 16 CIN I, 20 CIN II, 22 CIN III, and 40 cervical cancer tissues." (PMID 34671559, 2021). "We found that PAMR1 was negatively correlated to individual cancer stage, but not tumor grade of cervical cancer." (PMID 34671559, 2021). "However, there is no relevant research on the role of PAMR1 in the tumorigenesis and progression of cervical cancer." (PMID 34671559, 2021).
endometrial cancer (2 papers, 2021). Primary or metastatic malignant neoplasm involving the endometrium (mucous membrane that lines the endometrial cavity). "The LASSO regression model and survival analysis further suggested that two hub genes (PAMR1 and SLC24A3) could serve as potential biomarkers for the treatment or diagnosis of cervical and endometrial cancers." (PMID 34834529, 2021).
colon adenocarcinoma (1 paper, 2021). "Additionally, the expression of PAMR1 was also decreased in a variety of cancer types, such as colon adenocarcinoma (COAD), head and neck squamous cell carcinoma (HNSC), kidney chromophobe (KICH), liver hepatocellular carcinoma (LIHC), lung adenocarcinoma (LUAD), and rectum adenocarcinoma (READ)." (PMID 34671559, 2021).
coronary artery disease (1 paper, 2019). "PAMR1 has been found associated with the coronary artery disease in adipose tissue." (PMID 31983920, 2019).
gynecologic cancer (1 paper, 2021). "The results demonstrated that PAMR1 and SLC24A3 may serve as potential prognostic biomarkers in gynecologic cancer." (PMID 34834529, 2021). "Moreover, using GEPIA2, the expression of PAMR1 and SLC24A3 in tumor tissues was downregulated significantly compared with the normal tissue and was related to the OS of patients with gynecologic cancer." (PMID 34834529, 2021). "Finally, the results suggested that PAMR1 and SLC24A3 may act as prognostic biomarkers for gynecologic cancer in our study." (PMID 34834529, 2021).
meningioma (1 paper, 2017). A generally slow growing tumor attached to the dura mater. "AQP1, FRZB, PDGFRL, and PECAM1 were consistently underexpressed in meningioma samples; MEDAG, MYC, PAMR1, PDPN and PERP were consistently overexpressed in nearly every meningioma sample by both measurements." (PMID 29073243, 2017).
Obesity (1 paper, 2018). Accumulation of substantial excess body fat. "Several of the observed DMCs were located in genes related to T2D or obesity, such as ALOX12, PAMR1, and GNAS in WB; IRS1, LEP, and ADIPOQ in SAT; LCAT, FOXA2, KCNQ1, and GCKR in VAT; and PKD4, HNF4A, XBP1, and PON1 in LT." (PMID 29466957, 2018).
psoriasis (1 paper, 2014). An autoimmune condition characterized by red, well-delineated plaques with silvery scales that are usually on the extensor surfaces and scalp. "33% of PP-decreased DEGs (291/885) were expressed more highly in fibroblasts than any other cell type, of which TSPAN8 and PAMR1 were among the most strongly repressed in psoriasis lesions." (PMID 24885462, 2014).
cancer (5 papers, 2016 to 2023). A tumor composed of atypical neoplastic, often pleomorphic cells that invade other tissues. "PAMR1 influences epithelial-to-mesenchymal transition by inhibiting the proliferation, migration, and invasion of cancer cells." (PMID 38248716, 2023). "Since epithelial-to-mesenchymal transition (EMT) is an important biological process for the migration and invasion of cancer cells, we then analyzed the influence of PAMR1 on EMT markers." (PMID 34671559, 2021). "Additionally, gene set enrichment analysis (GSEA) showed a variety of cancer-related pathways potentially activated or suppressed by PAMR1." (PMID 34671559, 2021). "The roles and mechanisms of PAMR1 in other types of cancers are still unclear." (PMID 34671559, 2021). "However, the role of PAMR1 in other types of cancers is still unclear." (PMID 34671559, 2021). "The expression of PAMR1 and SLC24A3 in cancer tissue is downregulated significantly compared to normal tissue." (PMID 38248716, 2023).
tumor (5 papers, 2016 to 2022). "Consistent with our results, PAMR1 has long been considered an inhibitor of tumor activities such as spread, migration, and development in CC." (PMID 36091054, 2022). "Nevertheless, more in vivo experiments are needed to reveal the tumor-suppressor role of PAMR1 in greater detail." (PMID 34671559, 2021). "In agreement, a recent study identified a four gene antitumor signature related to the tumor microenvironment, which included RIPOR2, CCL22, PAMR1, and FBN1 genes." (PMID 36497200, 2022). "The boxplot demonstrated that mRNA expression levels of PAMR1 and SLC24A3 were significantly lower in tumor tissues than in normal samples (p < 0.05)." (PMID 34834529, 2021). "Among them, the expression of PAMR1 and SLC24A3 in tumor tissues was downregulated significantly compared to the normal tissue, and found to be statistically significant in survival rates between the CC and EC of patients (p < 0.05)." (PMID 34834529, 2021).
brain disorder (1 paper, 2025). A disease affecting the brain or part of the brain. "Of the significant reverse MR relationships, the brain disorders demonstrated associations with the increased expression of six proteins (PAMR1, MAVS, F11R, REN, GER and LEPR) and decreased expression of three proteins (TNFRSF4, BTN2A1, ENPP6)." (PMID 40456753, 2025).
PAMR1 also shares sentences with these, for which no sentence is quoted: cutaneous melanoma (1 paper); head and neck squamous cell carcinoma (1); ichthyosis (1); lung adenocarcinoma (1); lung carcinoma (1); muscular dystrophy (1); osteosarcoma (1); polycystic ovary syndrome (1); rectum adenocarcinoma (1).